CTNS (cystinosin, lysosomal cystine transporter)
Description:
Cystine/H(+) symporter that mediates export of cystine, the oxidized dimer of cysteine, from lysosomes. Plays an important role in melanin synthesis by catalyzing cystine export from melanosomes, possibly by inhibiting pheomelanin synthesis. In addition to cystine export, also acts as a positive regulator of mTORC1 signaling in kidney proximal tubular cells, via interactions with components of the v-ATPase and Ragulator complexes. Also involved in small GTPase-regulated vesicle trafficking and lysosomal localization of LAMP2A, independently of cystine transporter activity (By similarity).
Synonyms: CTNS-LSB; PQLC4; SLC66A4
Tractability: Small molecule: a structure with a bound ligand is known. Antibody: UniProt places it where antibodies can reach, with high confidence; its Gene Ontology location is reachable by antibodies, with high confidence; UniProt predicts a signal peptide or a membrane-spanning region.
Target class: Transporter
Gene: Protein-coding gene on chromosome 17 (3,636,459 to 3,663,103, forward strand). Ensembl gene ENSG00000040531.
Subcellular location: Lysosome membrane (Isoform 1); Melanosome membrane; Lysosome membrane (Isoform 2); Cell membrane
Subcellular location (Human Protein Atlas): Vesicles
Pathways (Reactome):
Transport of small molecules: Miscellaneous transport and binding events; SLC-mediated transport of oligopeptides
Gene Ontology:
Molecular function: L-cystine transmembrane transporter activity; solute:proton symporter activity
Biological process: ATP metabolic process; brain development; cognition; glutathione metabolic process; L-cystine transport; regulation of melanin biosynthetic process; regulation of TORC1 signaling; amino acid metabolic process; oligopeptide transmembrane transport; transmembrane transport; animal organ development; positive regulation of TORC1 signaling; proton transmembrane transport; system development
Cellular component: early endosome; extracellular exosome; late endosome; lysosomal membrane; lysosome; melanosome; melanosome membrane; plasma membrane
Genetic constraint (gnomAD): Loss-of-function variants: 22 observed, 41.65 expected, observed/expected ratio (o/e) 0.53, 90% interval 0.38 to 0.75. The upper end of that interval is the gene's LOEUF score, 0.75, which puts it in group 3 of 6, group 1 being the genes least tolerant of losing a copy. Missense variants: 408 observed, 445.19 expected, observed/expected ratio (o/e) 0.92, 90% interval 0.84 to 1. Synonymous variants: 169 observed, 179.48 expected, observed/expected ratio (o/e) 0.94, 90% interval 0.83 to 1.07.
Gene-disease validity (ClinGen):
ClinGen rates the evidence that CTNS causes each of these diseases.
cystinosis (autosomal recessive): Definitive. Cystinosis is a metabolic disease characterized by an accumulation of cystine inside the lysosomes, causing damage in different organs and tissues, particularly in the kidneys and eyes.
Homologues: Orthologues: chimpanzee CTNS (97% identical), macaque CTNS (89% identical), pig CTNS (87% identical), mouse Ctns (84% identical), rabbit CTNS (84% identical), dog CTNS (82% identical), rat Ctns (81% identical), guinea pig CTNS (72% identical), tropical clawed frog ctns (65% identical), zebrafish ctns (60% identical), Drosophila melanogaster Ctns (43% identical), Caenorhabditis elegans ctns-1 (37% identical).
Diseases named in the same sentence as CTNS in open-access papers:
CTNS is named in the same sentence as 66 diseases in open-access papers, as found by Europe PMC text mining. Sharing a sentence is not in itself a finding about the gene and the disease. The quoted sentences say what the papers report.
cystinosis (112 papers, 2006 to 2026). "Specific mutations have been reported in intermediate cystinosis patients and the 928 G>A (G197R) mutation in CTNS is associated with ocular cystinosis." (PMID 40369127, 2026). "The entire coding region of CTNS-cDNA was screened to identify mutations and polymorphisms in 10 families: 5 unrelated and 5 related families with cystinosis." (PMID 41749111, 2026). "This highlights the potential influence of genetic and/or environmental factors in addition to primary CTNS mutations on the muscle disease of cystinosis." (PMID 40369127, 2026). "All forms of cystinosis are caused by biallelic, pathogenic variants in the CTNS gene located on chromosome 17p21 and identified in 1998." (PMID 40369127, 2026). "In the absence of WBC cystine level assays, 71% of experts check for CTNS mutations in addition to clinical and biochemical manifestations indicative of nephropathic cystinosis." (PMID 40868444, 2025). "Mutations in CTNS lead to cystinosis, a rare autosomal recessive lysosomal storage disorder characterized by the pathological accumulation of cystine in various organs and tissues." (PMID 41199666, 2025). "Nephropathic Cystinosis (NC), which often manifests in early infancy, is caused by mutations in the CTNS gene and results in disruption of efficient transport of the amino acid cystine out of lysosomes." (PMID 40843950, 2025). "Nephropathic cystinosis (NC) is a rare autosomal recessive disease secondary to impaired activity of cystinosin, a lysosomal H + /cystine symporter encoded by the CTNS gene." (PMID 39540998, 2024). "Follow-up with nephrology included genetic testing for cystinosis, which revealed a homozygous gene variant of the CTNS gene with deletion of exons 1-10." (PMID 39055402, 2024). "Expression and localization of LAMP2A were inappropriate in cystine transporter cystinosis (CTNS) deficient cells, and degradation of CMA substrate was defective in Ctns −/− mice." (PMID 39273100, 2024). "European and Middle Eastern cystinosis patients have been found to carry a 57-kB genomic deletion, causing CTNS loss of function." (PMID 38380220, 2024). "The etiology of cystinosis has been identified as a monogenic disease from biallelic pathogenic variants in the CTNS gene located on chromosome 17p13." (PMID 39113682, 2024). "Cystinosis is a metabolic disease caused by pathogenic variants in the CTNS gene causing the cellular accumulation of cystine." (PMID 39113682, 2024). "Dysfunctional mutations in the CTNS gene encoding cystinosin cause cystine to accumulate in the lysosomes and form crystals in most tissues, leading to the life-threatening disease cystinosis." (PMID 37111358, 2023). "Cystinosis is a prototype lysosomal storage disorder caused by mutations in the CTNS gene, encoding the lysosomal cystine-H+ symporter cystinosin, and leading to cystine accumulation in all cells of the body." (PMID 38016974, 2023). "Nephropathic cystinosis is a rare lysosomal storage disorder with an incidence of 1 in 100 000–200 000 live births and is caused by mutations in the CTNS gene, which encodes the protein cystinosin." (PMID 36873093, 2023). "Cystinosis is an autosomal recessive disorder caused by bi-allelic mutations in the 17p13.2-located CTNS gene with an incidence rate of around one in 100,000 to 200,000 live births." (PMID 38087330, 2023). "It is the active substance in drugs employed in the treatment of cystinosis, a rare and autosomal recessive disorder caused by a mutation in the gene CTNS, which codes for cystinosis, the lysosomal cystine transporter." (PMID 37631061, 2023). "Nephropathic cystinosis is an autosomal recessive lysosomal storage disease in which the cystine transporter cystinosin is impaired due to mutations in the CTNS gene." (PMID 37219641, 2023). "Cystinosis is an autosomal recessive LSD caused by mutations in the CTNS gene encoding the carrier protein cystinosin that transports cystine out of the lysosomal compartment." (PMID 36713078, 2023).
cystinosis (continued). "Cystinosis, a rare lysosomal storage disease caused by mutations in the CTNS gene, is characterized by cystine crystallization and accumulation within multiple tissues, including kidney and brain." (PMID 38087330, 2023). "Cystinosis is an autosomal recessive lysosomal storage disease, caused by mutations in the CTNS gene, resulting in multi-organ cystine accumulation." (PMID 36674769, 2023). "Cystinosis is an ultrarare, autosomal-recessive lysosomal storage disease caused by mutations in the CTNS gene, which encodes a lysosomal transmembrane protein called cystinosin." (PMID 37514038, 2023). "Nephropathic cystinosis is a monogenic autosomal recessive lysosomal storage disorder caused by variants in the CTNS gene, which codes for cystinosin—the cystine lysosomal symporter." (PMID 35053306, 2022). "Prenatal diagnosis of cystinosis can be performed in at-risk pregnancies by molecular analysis of the CTNS gene in chorionic villi or circulating fetal cells." (PMID 35681534, 2022). "Nephropathic cystinosis is a rare autosomal recessive disorder characterized by amino acid cystine accumulation and caused by biallelic mutations in the CTNS gene." (PMID 35571017, 2022). "Several studies showed that CTNS splicing mutations have been described in all three clinical variants of cystinosis: classic nephropathic cystinosis, the intermediate variant, and the ocular form." (PMID 35524314, 2022). "Once the CTNS pathogenic variants have been identified in an affected family member, for a pregnancy at increased risk and preimplantation genetic diagnosis for cystinosis are possible." (PMID 35406673, 2022). "Variations c.257_258delCT and c.323delA reported in three Iranian patients in the CTNS gene are frameshifts, and truncating mutations that affect product function result in relatively mild symptoms of cystinosis." (PMID 35513889, 2022). "Owing to our patient’s prominent clinical features of cystinosis, we carried out a targeted search for mutations in the CTNS gene." (PMID 35513889, 2022). "Recessive mutations in the CTNS gene encoding the lysosomal transporter cystinosin cause cystinosis, a lysosomal storage disease leading to kidney failure and multisystem manifestations." (PMID 35137071, 2022). "The three forms of cystinosis are caused by mutations in CTNS, which encodes lysosmal membran cystinosin." (PMID 35524314, 2022). "Eight different Tunisian families with cystinosis were investigated in this study for both the molecular profile (CTNS mutations) and the ophthalmic examination." (PMID 35524314, 2022). "More than 90% of detected cystinosis cases are caused by a 57 kb deletion and mutations located in exons 7–10 and 12a of the CTNS gene, which mostly corresponds with international studies." (PMID 35571017, 2022). "Among the described CTNS variants, the 57 kb deletion was the most frequent; it was detected on 20 alleles (25.0%) in 15 (37.5%) children with infantile nephropathic cystinosis." (PMID 35571017, 2022). "At present, more than 140 mutations have been reported, with the infantile form of cystinosis being associated with severe CTNS mutations on both alleles, and the juvenile and ocular forms mostly being associated with milder mutations in at least one allele." (PMID 35681534, 2022). "The CTNS gene was identified in 1998 and to date more than 140 mutations have been linked to nephropathic cystinosis in patients around the world." (PMID 35977944, 2022). "The patient P5, with classical nephropathic cystinosis, was homozygosity for a novel splicing mutation in CTNS, c.681 + 7delc." (PMID 35524314, 2022). "Since then, approximately 150 CTNS pathogenic variants have been described in patients with cystinosis worldwide." (PMID 35406673, 2022). "In this case report, we reviewed the genetic basis of cystinosis and investigated two Iranian cases affected by cystinosis, one of which revealed a rare mutation in the CTNS gene." (PMID 35513889, 2022).
cystinosis (continued). "Cystinosis is a rare autosomal-recessive lysosomal storage disease caused by mutations in the CTNS gene that encodes the cystine transporter, cystinosin, which leads to lysosomal cystine accumulation." (PMID 35524314, 2022). "Owing to our patient’s prominent clinical features of cystinosis, we carried out a targeted search for CTNS gene mutations by sequencing the exonic regions." (PMID 35513889, 2022). "In this study, we review the genetic basis of cystinosis and confirm the association of important CTNS gene mutations with cystinosis." (PMID 35513889, 2022). "Nephropathic cystinosis (MIM219800) is a lysosomal storage disease (LSD) caused by mutations in CTNS, a gene that codes for the lysosomal cystine/proton symporter cystinosin." (PMID 34165243, 2021). "In our previous study, we have developed a zebrafish model of cystinosis through a nonsense mutation in the CTNS gene and have shown that zebrafish larvae recapitulate the kidney phenotype described in humans." (PMID 34502306, 2021). "Cystinosis is an autosomal recessive storage disorder caused by mutations in the CTNS gene which encodes the lysosomal cystine proton co-transporter cystinosin, carrying cystine from the lysosomal lumen to the cytosol." (PMID 34502306, 2021). "Cystinosis is a lysosomal storage disease caused by pathogenic variants in the gene CTNS, which encodes a lysosomal membrane cystine transporter, cystinosin." (PMID 33920837, 2021). "A nonsense mutation that creates a premature stop codon in exon 7 of CTNS (W138X) is commonly found in cystinosis patients in Canada, making this variant a key therapeutic target for this population." (PMID 35011573, 2021). "Cystinosis is a lysosomal storage disorder due to mutations in CTNS gene (encoding cystinosin) that is a proton-cystine symporter responsible for the secretion of cystine dimers and protons from the lysosomal lumen." (PMID 32377395, 2020). "As follows, we used targeted next generation sequencing to detect mutations in the promoter and exons of the CTNS gene in our cystinosis affected family member (patient V-3)." (PMID 33308164, 2020). "In this report, we present our strategy to advise a future couple of first cousins, whose descendants would risk cystinosis; an autosomal recessive lysosomal disease caused by mutations in the CTNS gene." (PMID 33308164, 2020). "This kind of mutation is the most characteristic and the most frequently described mutation in the CTNS gene that causes cystinosis." (PMID 33171856, 2020). "Cystinosis is caused by mutations in the CTNS gene, which encodes the cystine lysosomal transporter, cystinosin." (PMID 33292395, 2020). "The most frequent (50–70%) of CTNS mutations in Northen Europe is a large 57-kb which constitutes 75% of the mutated alleles in patients of Northern European descent with cystinosis; however, the spectrum of the mutations varies according to geography." (PMID 32727395, 2020). "Cystinosis disease is due to biallelic mutations in the CTNS gene (17p13.2), which is a gene of 12 exons cystinosin." (PMID 33308164, 2020). "Nephropathic cystinosis is a lysosomal disorder caused by functional defects of CTNS, a lysosomal 7-transmembrane protein H+-driven cystine transporter that mediates cystine efflux into the cytosol." (PMID 32784543, 2020). "Mutation in the gene CTNS that encodes for cystinosin is the main cause of the disease cystinosis, a rare autosomal recessive storage disorder characterized by defective lysosomal efflux of cystine." (PMID 33375025, 2020). "Nephropathic cystinosis is an inherited metabolic disorder caused by the lysosomal accumulation of cystine due to mutations in the CTNS gene encoding cystinosin, and leads to end-stage renal disease within the second decade." (PMID 32354056, 2020). "Cystinosis is an autosomal recessive lysosomal storage disorder (general incidence of 1:100,000–200,000 live births) caused by mutation of the CTNS gene." (PMID 30949462, 2019).
cystinosis (continued). "Cystinosis is a rare LSD characterized by massive accumulation of cystine in several body tissues caused by mutations of the CTNS gene, which encodes for cystinosin, a cystine-selective transport channel localized in the lysosomal membrane." (PMID 31284546, 2019). "Cystinosis is caused by mutations in the CTNS gene that encodes the lysosomal cystine carrier protein cystinosin." (PMID 31672123, 2019). "Nephropathic cystinosis is a rare lysosomal storage disorder caused by mutations in CTNS gene leading to Fanconi syndrome." (PMID 31888107, 2019). "Cysteamine is used in oral therapy to treat cystinosis, which is an autosomal recessive lysosomal storage disease caused by mutations in the CTNS, which is the gene encoding the protein cystinosin in human." (PMID 31519201, 2019). "The W138X mutation creates a premature STOP codon in the seventh exon of the CTNS gene and accounts for 40–50% of cystinosis alleles in Quebec." (PMID 31800572, 2019). "In this study, we explore the potential of ELX-02 to serve as a novel therapy for cystinosis caused by CTNS nonsense mutations." (PMID 31800572, 2019). "Cystinosis is an autosomal recessive disorder caused by mutations that disable the cystine transporter called cystinosin (CTNS)." (PMID 30591971, 2019). "Cystinosis is a rare autosomal recessive disorder caused by mutations of the CTNS gene, encoding a cystine-specific transporter (cystinosin) that facilitates cystine efflux through the lysosomal membrane." (PMID 31800572, 2019). "Nephropathic cystinosis is usually associated with two severe or truncating CTNS mutations that affect the promoter, leader sequence, transmembrane or non-transmembrane regions, including small deletions/insertions, missense and splicing mutations." (PMID 29260317, 2019). "Cystinosis is a rare autosomal recessive disorder caused by mutations in the CTNS gene, codifying for the lysosomal cystine-proton co-transporter cystinosin." (PMID 31709256, 2019). "Cystinosis is a lysosomal storage disorder (LSD) caused by genetic defects in CTNS (Ctns in mouse), the gene that codes for the cystine transporter cystinosin." (PMID 30774622, 2019). "Cystinosis is a rare autosomal recessive lysosomal storage disorder caused by mutations in the CTNS gene." (PMID 29594088, 2018). "This protein is encoded by the CTNS gene which is defective in the lysosomal storage disorder, cystinosis." (PMID 30513914, 2018). "Within the group of individuals with nephropathic cystinosis, truncating CTNS mutations, as well as the 57-kb deletion, result in a severe, infantile form of the disease." (PMID 30513914, 2018). "In humans, Pathogenic mutations of CTNS lead to defective cystinosin function, intralysosomal cystine accumulation and the development of cystinosis." (PMID 28198397, 2017). "Cystinosis is a rare autosomal recessive disorder characterized by lysosomal cystine accumulation due to loss of function of the lysosomal cystine transporter (CTNS)." (PMID 27734949, 2016). "When CTNS is mutated, cystine transport is disrupted, leading to cystine accumulation, the diagnostic hallmark of the lysosomal storage disorder cystinosis." (PMID 27142334, 2016). "Mutations in the CTNS gene results in massive accumulation of cystine in lysosomes and causes cystinosis (MIM 21980), a rare multisystemic disorder that represents the first cause of renal Fanconi syndrome in early childhood." (PMID 27148969, 2016). "Cystinosis is a rare autosomal recessive disease caused by mutations of the CTNS gene, which encodes for a lysosomal cystine/H+ symporter." (PMID 25947233, 2015). "Specifically, in the most populated Chinese population, there was only one Taiwan family with two sisters affected by intermediate cystinosis reported, which was the consequence of a homozygous missense mutation (N323K) of CTNS gene." (PMID 25866837, 2015).